BRCA1 (BRCA1 DNA repair associated)
Diseases named in the same sentence as BRCA1 in open-access papers (continued):
Sharing a sentence is not in itself a finding about the gene and the disease.
atherosclerosis (continued). "Of particular interest, pathway enrichment analysis of the 34 common gene associated DMRs revealed epigenetic impairment of NRF2 oxidative stress (SOD2), DNA repair (BRCA1), thioredoxin (TXNRD1) and inflammatory pathways (MIF, PLA2G4D) in atherosclerosis conditions." (PMID 28698603, 2017). "Moreover, BRCA1 and CRISP2 target genes demonstrate significant hypermethylation in atherosclerosis blood samples, as compared to blood samples derived from healthy individuals." (PMID 28698603, 2017). "In this study, we identified genomic regions in BRCA1 and CRISP2 which were consistently differentially methylated in blood DNA of atherosclerosis patients compared to healthy individuals, and in aortic and carotid plaque samples compared to aorta samples without plaque." (PMID 28698603, 2017). "Differentially methylated BRCA1 and CRISP2 regions were verified by MassARRAY Epityper and pyrosequencing assays and could be further replicated in blood, aorta tissue and carotid plaque material of atherosclerosis patients." (PMID 28698603, 2017). "However, observed atherosclerosis related DNA hypermethylation trend for most BRCA1 and CRISP2 CpG probes does not follow the expected methylation change in blood samples enriched for granulocyte and reduced CD8+ T immune cell subpopulations." (PMID 28698603, 2017). "As our data suggests, silencing of the BRCA1 gene in atherosclerosis patients may mean that this gene not only acts a tumor suppressor but also as a vascular protector against oxidative cell damage." (PMID 28698603, 2017). "We also identified other relevant novel networks and pathways, such as Antigen Presentation Pathway, Atherosclerosis Signalling, LXR/RXR Activation, and Role of BRCA1 in DNA Damage Response, whose dysregulation may each in part underlie their implication in the pathogenesis of RA." (PMID 23259760, 2012). "DNA methylation changes of the BRCA1 and CRISP2 DMRs could also be replicated in an Illumina 450 K dataset of paired atherosclerotic plaque and normal aorta samples from 24 middle aged men with subclinical atherosclerosis of the Aragon Workers Health Study (AWHS)." (PMID 28698603, 2017). "Of special note, the differentially methylated regions in BRCA1 and CRISP2 appeared to be largely independent of age and/or immune cell type composition, and both hold promise as valuable atherosclerosis related biomarkers in routine blood analysis." (PMID 28698603, 2017).
brain tumors (13 papers, 2011 to 2023).
endometriosis (13 papers, 2017 to 2026). The growth of functional endometrial tissue in anatomic sites outside the uterine body. "The authors found that the BRCA1 polymorphism rs71361504 (-/GTT) was significantly associated with the risk of endometriosis (p value < 0.0001) as highlighted in." (PMID 39359934, 2024). "The BRCA1 variants in endometriosis (c.3232T > A) and PCOS (c.2566T > C) were identified within an OCCR of the gene and two BRCA2 variants in POI (c.7579delG, c.8524C > T) were identified to be within BCCR regions of the gene." (PMID 39359934, 2024). "Here we find that the DNA damage response protein BARD1 is a target of miR-210-3p, and the BRCA1 complex is implicated in cell cycle regulation response to DNA damage under hypoxia in endometriosis." (PMID 30760709, 2019). "While BRCA1/2 mutations are established risk factors for ovarian cancer, their association with endometriosis remains unclear." (PMID 41440203, 2025). "Further characterization of this BRCA1 variant in eutopic endometrial tissue of endometriosis patients and controls identified significantly decreased BRCA1 protein expression as well as a loss of nuclear localization of the protein in patients with endometriosis." (PMID 39359934, 2024). "Serum AMH concentration showed a significant correlation with ovarian BRCA1 mRNA expression in women with endometriosis (p = 0.03)." (PMID 30622513, 2018). "Serum AMH concentration and ovarian BRCA1 mRNA expression correlated significantly in the endometriosis group (correlation coefficient, 0.541; p = 0.03)." (PMID 30622513, 2018). "Endometrial expression of BRCA1 and Rad51 mRNA proved significantly lower in the endometriosis group (vs. controls), as did ovarian expression of BRCA1 and BRCA2 mRNA." (PMID 30622513, 2018). "Decreased expression of BRCA1 protein in endometrial and ovarian tissues of the endometriosis group was confirmed by immunofluorescence staining." (PMID 30622513, 2018). "Endometriosis is associated with variants in XRCC3, BRCA1 and CSB genes." (PMID 39359934, 2024). "Indeed, expression levels of BRCA1, Rad51, and ATM in endometrial tissue proved to be lower in the endometriosis group than in control subjects, as were expression levels of BRCA1 and BRCA2 in ovarian tissue." (PMID 30622513, 2018).
leiomyosarcoma (13 papers, 2009 to 2025). An uncommon, aggressive malignant smooth muscle neoplasm, usually occurring in post-menopausal women. "This action is in agreement with a recent report describing the ability of BRCA1 deficiency to accelerate uterine leiomyosarcoma development." (PMID 20046869, 2009). "Since BRCA1, a well-known tumor suppressor gene, plays a role in maintaining genomic stability, loss of BRCA1 function potentially is involved in the progression of leiomyosarcoma." (PMID 24649216, 2013). "BRCA1 mutations were identified in 29 patients – 23 in the STS cohort, four with bone cancer, one with GIST, and one with uterine sarcoma (uterine leiomyosarcoma)." (PMID 36741731, 2022). "One study has shown that 29% (25 of 85) of human uterine leiomyosarcomas are negative for BRCA1 immunohistochemical staining." (PMID 27643881, 2016).
Cowden syndrome (12 papers, 2008 to 2026). "Currently, the NHS guidelines to the UK genetics departments allow estimation of BRCA1/2 and PALB2 (as well as syndromic genes where indicated such as PTEN in Cowden disease)." (PMID 33317064, 2020).
Huntington disease (12 papers, 2009 to 2021). Huntington disease (HD) is a rare neurodegenerative disorder of the central nervous system characterized by unwanted choreatic movements, behavioral and psychiatric disturbances and dementia. "Our interested top ten common canonical pathways associated with Elp1 deficiency include Huntington’s disease signaling, acute phase response signaling, senescence pathway, and role of BRCA1 in DNA damage response." (PMID 34819065, 2021). "Several studies demonstrated that BRCA1 deficiency contributes to neuronal injury in Huntington’s Disease and impairs cognitive function in mice." (PMID 32381096, 2020). "This is based on guidelines regarding Huntington’s disease in anticipation of high psychosocial impact of DNA-testing for mutations in BRCA1/2 genes." (PMID 22569005, 2012). "Other examples of successful HuMMs to study the role of genetic mutations are found in common monogenic disorders such as Huntington disease and β-thalassemia, as well as cancer susceptibility genes such as BRCA1." (PMID 22396661, 2012). "The genetic conditions that are met with an adequate provision of genetic services in Quebec, as indicated by the respondents, are BRCA1/2, cardiovascular diseases, Huntington disease, and neurological conditions (e.g., Alzheimer, Parkinson)." (PMID 32194621, 2020). "In striatal cell lines modelling Huntington’s disease, BRCA1 recruitment to sites of DNA damage was impaired due to an imbalance in active and inactive BRCA1 levels, resulting in delayed DNA repair and persistent double-stranded break accumulation from a disruption in the signalling pathway." (PMID 34222870, 2021). "Striatal BRCA1 levels are altered in a Huntington's disease model." (PMID 26615780, 2015). "De-regulation in Brca1 expression had been reported in Alzheimer’s and Huntington’s diseases." (PMID 26227626, 2015).
Parkinson disease (12 papers, 2008 to 2024). A progressive degenerative disorder of the central nervous system characterized by loss of dopamine producing neurons in the substantia nigra and the presence of Lewy bodies in the substantia nigra and locus coeruleus. "When comparing potential molecular biomarkers for Parkinson’s Disease (PD) like EGF, BRCA1, LEPR, and APP with recognized biomarkers, it’s essential to understand the context of their roles and advantages in PD." (PMID 39264583, 2024). "Second, future studies are needed to determine whether BRCA1 also colocalizes with tau in other tauopathies, such as argyrophilic grain disease, chronic traumatic encephalopathy, tangle-only dementia, amyotrophic lateral sclerosis, and parkinsonism–dementia complex, and globular glial tauopathy." (PMID 31861888, 2019). "Well known examples are deregulation of the E3s BRCA1, Mdm2, VHL and Skp2 in various cancers, and Parkin in Parkinson's disease." (PMID 18213395, 2008).
psychological distress (12 papers, 2007 to 2025). "The results uncover the high prevalence of menopausal symptoms following RRSO in BRCA1/2 mutation carriers, with psychological distress frequently mirroring the severity of somatic–vegetative and urogenital discomfort." (PMID 39201170, 2024). "There are few studies that address illness representations, coping, and psychological distress in BRCA1/2 mutation carriers." (PMID 34069035, 2021). "This study aimed to examine the relationship among illness representations, coping strategies and psychological distress (i.e., cancer worry and depressive symptoms) in BRCA1/2 mutation carriers." (PMID 34069035, 2021). "Since the introduction in clinical practice of genetic testing for BRCA1/2 gene mutations, there has been a rising interest in eventual psychological distress caused by testing." (PMID 32089686, 2020). "This is the first paper to report uptake of risk management options, psychological distress and insurance problems in a large UK clinical cohort of men and women 3 years following predictive testing for BRCA1/2 mutations." (PMID 17285126, 2007). "Research has focused on psychological distress experienced by women following predictive BRCA1/2 testing." (PMID 17285126, 2007). "In line with the study’s hypotheses, coping self-efficacy was negatively correlated with the experience of psychological distress in newly BRCA1/2-positive women." (PMID 36767056, 2023). "In this study, we have shown that BRCA1 or BRCA2 mutation carriers have high levels of psychological distress irrespective of a history of cancer." (PMID 34635688, 2021). "In line with previous research, our results from the NCCN Distress Thermometer, PHQ-9 and GAD-7 demonstrated significant psychological distress among BRCA1 and BRCA2 mutation carriers, independent of a history of cancer." (PMID 34635688, 2021). "The literature regarding cancer genetic counseling for BRCA1/2 genes has consistently found that about 10% of patients who undertake the counseling procedure develop clinically significant symptoms of psychological distress, both in the long and short term, and with a positive test result." (PMID 30061853, 2018). "Furthermore, while cancer-affected BRCA1/2 carriers experience psychological distress and burden, all BRCA1/2 carriers may feel overwhelmed by the possibility of passing PV on to their offspring." (PMID 40596937, 2025). "Analyzing a survey data of 79 carriers of a BRCA1 or BRCA2 mutation, the majority had general psychological distress independent of cancer diagnosis in the patients’ history." (PMID 34635688, 2021).
viral infection (12 papers, 2004 to 2025). "Amongst these autophagy receptors, NBR1 (neighbor of BRCA1), a ubiquitin-binding scaffold protein, increases in viral infections, and NBR1 accumulates and is abnormal in IBM muscle." (PMID 38693436, 2024). "For example, besides its classical DNA damage repair function, BRCA1 gains multiple new functions including regulation of immunity against viral infection, gene expression, neural development, and reproduction." (PMID 38575974, 2024). "Single and double proximity ligation microscopy, immunoprecipitation, EdU-genome labeled virus infection, and chromatin immunoprecipitation studies demonstrated that H2B is associated with IFI16 and BRCA1 in the nucleus in physiological conditions." (PMID 27764250, 2016). "Gene expression in HCC1937 cells following virally mediated expression of wild-type BRCA1 was compared to gene expression following viral infection of GFP which was employed as an irrelevant infection control." (PMID 15383145, 2004). "BRCA1 expression was also demonstrated using Western blotting which confirmed BRCA1 protein expression following viral infection." (PMID 15383145, 2004). "While its classical function is DNA damage repair through HR and NHEJ pathways, human BRCA1 gains multiple new functions, including regulation of immunity against viral infection, regulation of gene expression, regulation of neural development, and reproduction enhancement." (PMID 37511102, 2023). "A study showed that histone H2B interacted with IFI16 (gamma-interferon-inducible protein 16) and BRCA1 in the nucleus, and viral infections such as EBV, KSHV and HSV-1 induced the cytoplasmic distribution of H2B-IFI16 and H2B-BRCA1 complexes via Ran-GTP protein." (PMID 34868031, 2021). "Four signaling pathways (interferon signaling, BRCA1/DNA damage response, PKR/INF induction and LGALS8), which may control the viral infection, are clearly associated with the BEN+ phenotype in SMs." (PMID 27280726, 2016). "Moreover, upregulation of cyclins, cell cycle control of chromosomal replication, and the role of BRCA1 in DNA damage response, alongside downregulation of the cell cycle G1/S checkpoint, suggest that HCoV-229E may favors S phase for viral infection." (PMID 33630927, 2021). "This preliminary experiment demonstrated that viral infection did in fact result in a 3.4 fold higher BRCA1 expression compared to the GFP control (data not shown)." (PMID 15383145, 2004). "While viral infections, including HCMV and HSV-1, have been shown to modulate Brca1 expression, no such relationship has been described for HSV-2." (PMID 40872306, 2025).
ataxia telangiectasia (11 papers, 2013 to 2025). Ataxia-telangiectasia is the association of severe combined immunodeficiency (affecting mainly the humoral immune response) with progressive cerebellar ataxia. "BRCA1/2 are responsible for homologous recombination of DNA and influence DNA repair (double-strand break – DSB), which are caused by ataxia–telangiectasia (AT)." (PMID 34362406, 2021). "Seven of these patients were found to carry two pathogenic variants including one biallelic ATM carrier with a clinical diagnosis of ataxia-telangiectasia, two ATM/BRCA2 carriers, one BRIP1/BRCA2 carrier, one BRCA1/CHEK2 carrier, one BARD1/PALB2 carrier, and one CHEK2/PALB2 carrier." (PMID 28008555, 2017).
Fibroadenoma (11 papers, 2009 to 2026). A benign tumor of the breast characterized by the presence of stromal and epithelial elements. "The right-sided breast lump which was diagnosed clinically as a fibroadenoma later turned out to be stage IIb pT3N0M0 metaplastic breast carcinoma with BRCA1 positivity and mutations in SMARCA4." (PMID 36027825, 2022). "Although malignant transformation in a fibroadenoma is rare, high suspicion index in middle aged women with fibroadenoma and associated risk factors like strong family history and/or BRCA-1, BRCA-2 mutation is recommended." (PMID 20072677, 2009). "In Israeli BRCA PV carriers, the number of biopsies, BRCA1 PV carriership were associated with an increased risk for developing BC, whereas fibroadenoma does not increase that risk." (PMID 40694193, 2025). "In conclusion, among Israeli BRCA PV carriers, a correlation between the number of breast biopsies being an older BRCA1 PV carrier and subsequent BC risk was noted, with fibroadenoma not being a forerunner of BC risk in BRCA carriers." (PMID 40694193, 2025). "Fibroadenoma (FA) was diagnosed in 235 participants (134 BRCA1 carriers and 101 BRCA2 carriers)." (PMID 40694193, 2025). "Rates of BC in women undergoing at least two benign biopsies were correlated with the number of biopsies, being an older BRCA1 PV carrier, whereas having been diagnosed with fibroadenoma—seems not to increase BC risk." (PMID 40694193, 2025). "However, in our study, BRCA1 tumors tended to have well-defined and rough margins, high depth-width ratio, and hypervascularization, which are uncommon features of benign tumors like fibroadenoma." (PMID 36905492, 2023). "However, unlike BRCA2, 29.5% of BRCA1 mutations display posterior echo enhancement, usually in benign breast lesions, such as fibroadenomas or cysts." (PMID 35402620, 2022). "We also included 27 non-cancerous breast samples in the study (23 fibroadenomas, 3 mammary reduction, and 1 BRCA1 prophylactic mastectomy)." (PMID 31992741, 2020).
biliary tract cancer (10 papers, 2020 to 2026). "Overall occurrence of BRCA mutations in biliary tract cancers has been reported as 3.6% with a BRCA2 predominance (0.6% have a BRCA1 mutation and 3% have a BRCA2 mutation)." (PMID 38903278, 2024). "BRCA1/2 mutations occur at 1–7% across biliary tract cancers (BTCs), but a broader spectrum of DDR gene alterations is reported in 28.9–63.5% of newly diagnosed BTC patients." (PMID 32878011, 2020). "Driver genes, such as the ERBB2, PIK3CA, IDH1/2, BRCA1/2, and FGFR2 fusion genes, have been identified in gallbladder and biliary tract cancers." (PMID 34573929, 2021).
carcinoma in situ (10 papers, 2008 to 2024). "For patients with in situ carcinoma, the BRCA1/2 double mutation frequency was 0.10% (2/2079), and the BRCA1/2 and PALB2 triple mutation frequency was 0.05% (1/2079)." (PMID 38439896, 2024). "Patient P1, who was diagnosed with carcinoma in situ at the age of 35, carries a BRCA1 gene with deletions of exons 11–13." (PMID 25176351, 2014). "In women with a germline mutation in BRCA1 or BRCA2, occult malignancy of serous histology, intraepithelial carcinoma or dysplasia is frequently found in the fimbrial end of the FT at the time of prophylactic surgery." (PMID 18612378, 2008). "In situ carcinoma was significantly observed in 32% of patients with BRCA1/2 VUS with respect to the 11.2% of patients without BRCA1/2 variant (p = 0.005, Fisher Exact test)." (PMID 32806537, 2020).